NRAS (NRAS proto-oncogene, GTPase)
Diseases named in the same sentence as NRAS in open-access papers (continued):
Sharing a sentence is not in itself a finding about the gene and the disease.
colorectal cancer (continued). "Distribution of coexisting subclonal mutations in EGFR, KRAS, and NRAS in a subset of the patients with fusion-present colorectal cancer suggests that these fusions may arise as a novel mechanism of resistance to anti-EGFR therapies in patients with metastatic colorectal cancer." (PMID 33015522, 2019). "Colorectal cancer (CRC) remains a major cause of cancer-related deaths in advanced disease, and activating KRAS/NRAS mutations limit the use of anti-EGFR antibodies to RAS-wild-type tumors." (PMID 41683587, 2026). "Although RAS mutations are highly prevalent in colorectal cancer (approximately 40% KRAS and 4% NRAS), until recently, they were considered ”undruggable”." (PMID 40731762, 2025). "Previous studies have validated the efficacy of CT-based radiomic models in predicting KRAS, NRAS, and BRAF mutations in colorectal cancer." (PMID 41409606, 2025). "Mutations in RAS genes (NRAS and KRAS) play a significant role in the pathogenesis of colorectal cancer." (PMID 41228322, 2025). "In colorectal cancer, mutations in the RAS gene family (mostly KRAS and NRAS) lead to the synthesis of actively functioning RAS proteins." (PMID 40731832, 2025). "Many colorectal cancers acquire driver mutations in genes in the MAPK/ERK signaling pathway, including heterozygous missense changes in KRAS, NRAS, or BRAF." (PMID 39751654, 2025). "The actionable colorectal cancer genes KRAS, NRAS, and BRAF were equally mutated in both phenotypes (q-values: 0.49, 0.97, and 0.97, respectively)." (PMID 40702107, 2025). "In people with and without disabilities, EGFR gene tests related to lung cancer and KRAS and NRAS gene tests related to colorectal cancer appeared as the top genetic test items among people aged ≥40 years." (PMID 38711356, 2024). "Colorectal cancer (CRC) is the leading cancer among Saudis, and mutations in BRAF, KRAS, and NRAS genes are therapeutically significant due to their association with pathways critical for cell cycle regulation." (PMID 39635441, 2024). "The study employed the TruSight Tumor 15 next-generation sequencing (NGS) panel on 86 colorectal cancer (CRC) samples to detect somatic mutations in BRAF, KRAS, and NRAS genes." (PMID 39635441, 2024). "At present, NRAS/KRAS mutations are widely considered to be associated with poor prognosis in a variety of cancers, including colorectal cancer and serous ovarian cancer." (PMID 38510490, 2024). "In a 190 colorectal cancer cohort, we identified seven somatic mutations in KRAS, NRAS and BRAF as well as five MSI loci (D2S123/D5S346/D17S250/BAT‐25/BAT‐26) simultaneously." (PMID 36583506, 2023). "The frequency of RAS mutations in colorectal cancer has been reported to be 50%–60% for KRAS, NRAS, and HRAS." (PMID 37760533, 2023). "For example, in the analysis of KRAS, NRAS, and BRAF mutations in 850 colorectal cancer (CRC) cases, the concordance rate was 88.6%, accounting for all mutations including those not in the Idylla cartridge by design." (PMID 37174112, 2023). "The highest frequency of gene rearrangements was seen in KRAS/NRAS/BRAF wild-type colorectal carcinomas (53/204 (26%))." (PMID 37686416, 2023). "For instance, mutations of the Kristen rat sarcoma virus (KRAS) and neuroblastoma RAS viral oncogene (NRAS) are encountered in approximately 44.7% and 7.5%, respectively, of all colorectal carcinoma cases." (PMID 37108476, 2023). "In colorectal cancer, NRAS is decreased significantly in cancerous tissues, and miR-144 can inhibit NRAS expression as well as the growth and migration of SW480 cells." (PMID 35339759, 2022).
colorectal cancer (continued). "This suggests that overexpression of HER2 is more likely to occur in patients with left hemicolorectal cancer and KRAS/NRAS/BRAF WT colorectal cancer." (PMID 35365123, 2022). "In this manner, the IdyllaTM mutation tests were validated for the detection of clinically significant KRAS, NRAS, and BRAF mutations in FFPE samples from colorectal cancer patients." (PMID 35474548, 2022). "To date, the CE-IVD IdyllaTMKRAS Mutation Test and the IdyllaTMNRAS-BRAF Mutation Test have been developed to detect KRAS, NRAS, and BRAF mutations in colorectal cancer patients." (PMID 35474548, 2022). "The combination was tested in vivo in seven patient-derived xenograft (PDX) models (five colorectal carcinoma and two papillary thyroid carcinoma models) with different KRAS, BRAF, and NRAS mutations." (PMID 35075200, 2022). "In patients with colorectal carcinoma metastasis, KRAS and NRAS mutations are tested prior to anti-epidermal growth receptor (EGFR) target therapy, as mutated RAS proteins downstream of EGFR will impair treatment effectiveness." (PMID 35328664, 2022). "To define the capacity of colorectal cancer organoids to mirror the genome heterogeneity of the corresponding patient tumor, we compared the mutational status of three genes (KRAS, NRAS, and BRAF) in 19 PDTOs and corresponding tumor tissues." (PMID 34359661, 2021). "It has been found that hsa_circ_0001955/miR-145-5p is the key axis in the carcinogenesis of colorectal cancer and in vitro, hsa_circ_0001955 promotes hepatocellular carcinoma cell proliferation, migration, and invasion via miR-145-5p/NRAS." (PMID 34532284, 2021). "A total of 146 colorectal cancer samples were sent to Nantes University Hospital between 1 January and 31 December 2019, to test for KRAS, NRAS or BRAF mutations by NGS and microsatellite instability by MSI-PCR." (PMID 34439357, 2021). "Mutation in KRAS, NRAS, and BRAF has been demonstrated to be involved in initiation and progression of colorectal carcinoma." (PMID 33816307, 2021). "These new experiments further support a mechanism in which cetuximab inhibits wild-type (HRAS and NRAS) signals in KRAS G13D colorectal cancers." (PMID 33153459, 2020). "As a result, epidermal growth factor (EGF), MAP2K2, MCC (mutated in colorectal cancer), and NRAS (neuroblastoma RAS viral oncogene homolog) were determined as remarkably prognostic-related genes." (PMID 33553243, 2020). "Our results demonstrated the BNA-clamp PCR method with Sanger sequencing have high accuracy for the detection of KRAS, NRAS and BRAF mutations in colorectal cancer." (PMID 31711486, 2019). "We explored the association of clinico-pathological variables related to the mutational status of KRAS, NRAS, BRAF, and PIK3CA, genes that are involved in the main pathways of different solid tumors including colorectal cancer." (PMID 31036005, 2019). "Overall, we confirmed the clinical utility of BNA-clamp PCR for detecting KRAS, NRAS and BRAF mutations in colorectal cancers." (PMID 31711486, 2019). "In colorectal cancer, Kirsten-RAS (KRAS) and neuroblastoma-RAS (NRAS) are the commonly mutated isoforms." (PMID 31816869, 2019). "NRAS mutations are considered rare in CRC, with one study detecting NRAS mutations in 2.2% of the 225 colorectal cancer cases.." (PMID 31881025, 2019). "Binimetinib, an inhibitor of MEK1/2, can enhance the effect of cetuximab in neuroblastoma RAS viral oncogene homolog (NRAS)-mutant colorectal cancer cells." (PMID 31527477, 2019). "In this study, we estimated the performance of BNA-clamp PCR with Sanger sequencing method to detect KRAS, NRAS and BRAF mutations in colorectal cancers and compared the results from PCR-rSSO and NGS." (PMID 31711486, 2019).
colorectal cancer (continued). "The aim of FOCUS4-D was to test the efficacy of AZD8931 in patients with colorectal cancer whose tumours are wild-type for BRAF, PIK3CA, KRAS, and NRAS mutations." (PMID 29254887, 2018). "NRAS in subnetwork 7 was indicated to have a potentially functional relationship with colorectal cancer and thyroid cancer." (PMID 30532734, 2018). "It is of note, however, that the in vivo xenograft experiment was carried out with a colorectal cancer line, HT-29, that is wild-type for KRAS and NRAS, but harbors the activating V600E mutation in the BRAF gene." (PMID 30410004, 2018). "Currently, the most clinically significant mutated genes in colorectal cancer are KRAS, NRAS and BRAF as these genes provide information on a patients’ prognosis and their suitability for anti-EGFR therapies." (PMID 29029407, 2017). "A final missense mutation (p.Phe894Cys) in Neurofibromin 1 (NF1), a tumor suppressor gene and a negative regulator of NRAS, is predicted pathogenic by SIFT/PolyPhen-2 and has been reported in association with one colorectal cancer by TCGA." (PMID 29254223, 2017). "We immunohistochemically evaluated EZH2 expression and assessed miR-31 and gene mutations [KRAS (codon 61/146), NRAS (codon 12/13/61), and BRAF (codon 600)] in 109 patients with colorectal cancer harboring KRAS (codon 12/13) wild-type." (PMID 28147317, 2017). "In metastatic/advanced colorectal cancer, a patient’s suitability for treatment with anti-EGFR monoclonal antibodies is determined by the presence of mutations in KRAS and/or NRAS." (PMID 29029407, 2017). "NRAS is approximately 4.3 kb in length and is aberrantly expressed in many tumors, including colorectal cancer and cutaneous melanoma." (PMID 27556696, 2016). "Most prevalent in colorectal cancer are KRAS exon 2 mutations (40% prevalence); lower prevalence is observed for KRAS exon 3 and 4 mutations (6%) and NRAS exon 2, 3, and 4 mutations (5%)." (PMID 27685259, 2016). "Somatic mutations in KRAS, NRAS, and BRAF genes are related to resistance to anti-EGFR antibodies in colorectal cancer." (PMID 25954997, 2015). "The additional mutations in minor KRAS, NRAS, and BRAF were detected in 20% of the colorectal cancer patients in the PEAK study." (PMID 25954997, 2015). "The panel allows the detection of mutations that are currently considered as actionable (NRAS, KRAS) or putatively actionable (BRAF, PIK3CA) in colorectal cancer." (PMID 26047774, 2015). "We have established a NGS mutation assay for the detection of KRAS, NRAS, and BRAF mutations in clinical FFPE samples of colorectal cancer and have demonstrated a high preclinical and clinical performance." (PMID 25954997, 2015). "Mutations in genes such as KRAS, NRAS, BRAF and PIK3CA have become an important part of colorectal carcinoma evaluation." (PMID 26691448, 2015). "In colorectal carcinomas, 1 case presented concomitant KRAS and NRAS mutations and 2 cases had concomitant G12D and G13D KRAS mutations." (PMID 26435479, 2015). "As current clinical practices in colorectal cancer revolve around KRAS, NRAS, and BRAF mutation status, diagnostic sequencing of either primary or metastatic tissue as available is acceptable for most patients." (PMID 25164765, 2014). "Recently, a broader mutation testing of RAS gene (at exons 2, 3, or 4 of both KRAS and NRAS) has been validated for treatment personalization in advanced colorectal cancer through the support of several studies." (PMID 24691006, 2014). "Mutation profiles were 100% concordant for KRAS, NRAS, and BRAF, and were highly concordant for recurrent alterations in colorectal cancer." (PMID 25164765, 2014).
colorectal cancer (continued). "However, consistent with other findings, POLE-mutated colorectal cancers were significantly associated with younger age, right-sided colon location, poor histological grade, early stage, and KRAS/NRAS/BRAF wild-type status." (PMID 40310397, 2025). "Seventeen colorectal cancers harboring a V600E mutation also presented with additional, predicted pathogenic mutations in KRAS, NRAS, or NF1 (17/709, 2.40%), comprising 13 colorectal cancers with NF1-inactivating mutations and four with KRAS mutations (4/709, 0.71%, mostly G12D)." (PMID 39751654, 2025). "Compared to existing molecular tools for colorectal cancer staging—such as APC, KRAS, BRAF, NRAS and PIK3CA mutations—our study offers a novel transcriptomic perspective by identifying stage-specific gene expression signatures that distinguish adenoma, CIS and adenocarcinoma." (PMID 40362431, 2025). "While KRAS/NRAS mutations are well known to predict a lack of efficacy from anti-EGFR antibodies in colorectal cancers, studies investigating the addition of the EGFR TKI erlotinib to chemotherapy in advanced BTC and PDA suggested a similar pattern." (PMID 40507311, 2025). "The meta-analysis supports the use of EGFR mAbs in the treatment of mCRC without mutations in KRAS, particularly for left-sided colorectal cancer and where the tumour does not harbour NRAS or BRAF mutations." (PMID 38402342, 2024). "In this study, we aimed to evaluate the expression of SEMA7A, SEMA4D, ADAM8, and ADAMTS10 in colorectal cancer (CRC) in relation to the mutational landscape of KRAS, NRAS, BRAF, PIK3CA, and AKT genes, microsatellite instability (MSI) status, and clinicopathological features." (PMID 39329961, 2024). "Mutations in the related NRAS gene were observed in 7% of non-CDX2-suppressed colorectal cancers and in no cases of the CDX2-suppressed group (Fisher’s exact test p = 0.02)." (PMID 39452477, 2024). "In colorectal cancer (CRC), NRAS mutations are rare compared to KRAS, but may lead to worse outcomes." (PMID 39451209, 2024). "The potential interplay or distinct impact of mutations within the EGFR pathway (EGFR, KRAS, NRAS, BRAF, PI3KCA), along with polymorphisms in genes related to 5-fluorouracil and oxaliplatin (DPYD, TYMS, GSTP1, MTHFR, ABCB1), on the prognosis of colorectal cancer remains uncharted territory." (PMID 38248103, 2024). "Furthermore, colorectal cancer is a highly heterogeneous clinical entity; genetic KRAS, NRAS, BRAF, or HER2 genes also work as the critical diagnostic and prognostic biomarkers." (PMID 36831695, 2023). "Previous studies have shown that simultaneous BRAF gene and NRAS gene mutations are virtually absent in individual colorectal cancer patients." (PMID 37037831, 2023). "KRAS, NRAS, BRAF V600E Mutations, DNA Mismatch Repair Deficiency/Microsatellite Instability Status, HER2 Amplification, and NTRK Fusions are NCCN approved and actionable molecular biomarkers for colorectal cancer." (PMID 36980565, 2023). "Although none of the sixty patients tested carried mutations of NRAS this is compatible with the known mutation frequency in colorectal cancer of about 3%." (PMID 36230756, 2022). "The IdyllaTMKRAS and NRAS-BRAF Mutation Tests have been developed for the qualitative detection of mutations in KRAS, NRAS and BRAF genes, facilitating the genomic profiling of patients with colorectal cancer." (PMID 35474548, 2022).
colorectal cancer (continued). "Interestingly, these POLE mutations were predominantly associated with KRAS, NRAS, BRAF, and/or PIK3CA mutations, commonly found in colorectal cancers." (PMID 35624529, 2022). "We hypothesised that plasticity in signal transduction may be a mechanism of drug resistance and tested this hypothesis in the setting of cetuximab resistance in patients with KRAS/NRAS/BRAFV600 wild-type colorectal cancer (CRC)." (PMID 34462871, 2021). "As a result, colorectal cancer patients harboring KRAS or NRAS have shorter overall survival (OS)." (PMID 34301278, 2021). "In addition, the SEER program lacks several important biomarker expression states, such as MSI, NRAS, KRAS, and BRAF, which were closely associated with metastases in colorectal cancer." (PMID 34055605, 2021). "KRAS, NRAS, and BRAF mutations are commonly present in colorectal cancer (CRC)." (PMID 33979337, 2021). "In addition, cartridges that are able to detect the most relevant genetic alterations of both the BRAF and NRAS genes in a single assay are now available, and they can be also used in other tumors harboring such alterations (i.e., colorectal cancer)." (PMID 32751423, 2020). "Modern diagnostics for colorectal cancer detect mutations in KRAS, NRAS, and EGFR genes." (PMID 32774122, 2020). "MAP2K1 mutation has been identified among subsets of smoking-associated lung carcinomas (mutually exclusive from EGFR, BRAF, KRAS, and NRAS mutations), lung adenocarcinoma in situ and early invasive disease, and KRAS/NRAS/BRAF/PIK3CA wild-type (“quadruple-wild-type”) colorectal carcinomas." (PMID 32483240, 2020). "About 40% of colorectal cancers are KRAS mutated, 5% NRAS mutated, and rarely HRAS mutated." (PMID 31803624, 2019). "BNA-clamp PCR accurately detected KRAS, NRAS and BRAF mutations in patients with colorectal cancer." (PMID 31711486, 2019). "KRAS, NRAS and BRAF mutations occur in colorectal cancers in a mutually exclusive manner." (PMID 31711486, 2019). "Several studies indicated that different mutation types of KRAS, NRAS, and BRAF gene in colorectal cancer tissues have different biological characteristics and lead to different biological changes, which may have different effects on patients." (PMID 30416987, 2018). "In this study, we systematically described and statistically analyzed the frequencies and distributions of KRAS/NRAS/BRAF genetic mutation status and their relationship with IHC in 260 cases with colorectal cancer or gastric cancer through retrospective analysis." (PMID 30416987, 2018). "Our findings indicate there are several histological patterns of OM in colorectal cancer, and that OM has no relation to NRAS and BRAF mutation." (PMID 29029440, 2017). "Accordingly, recent studies in genetically modified animals confirm that mutant NRAS might accelerate colorectal cancer development in the setting of inflammation." (PMID 27636997, 2016). "The KRAS, NRAS and BRAF mutations in colorectal cancer are normally mutually exclusive." (PMID 26968814, 2016). "Given the known resistance mechanisms of MEK inhibition in colorectal cancer, we hypothesized that tumors with known KRAS/NRAS or BRAF mutations that were PIK3CA wild-type would exhibit greater sensitivity to MEK inhibition." (PMID 26439693, 2015). "KRAS and NRAS mutations have been identified as negative predictive markers for cetuximab and panitumumab efficacy in colorectal cancer." (PMID 26149458, 2015). "In addition to KRAS mutation, genetic alterations in NRAS, HRAS, BRAF, and RAF1 were found in colorectal cancer samples analyzed in this study." (PMID 23700467, 2013). "Similarly, the KRAS G12C inhibitors sotorasib and JDQ443 had also displayed inhibitory effects on HRAS G12C and NRAS C12C, with the combination therapy of sotorasib and EGFR antibody panitumumab being successfully used to treat a patient with colorectal cancer with NRAS p.G12C mutation." (PMID 40304209, 2025).